CARD8 (caspase recruitment domain family member 8)
Description:
Inflammasome sensor, which mediates inflammasome activation in response to various pathogen-associated signals, leading to subsequent pyroptosis of CD4(+) T-cells and macrophages. Inflammasomes are supramolecular complexes that assemble in the cytosol in response to pathogens and other damage-associated signals and play critical roles in innate immunity and inflammation. Acts as a recognition receptor (PRR): recognizes specific pathogens and other damage-associated signals, such as HIV-1 protease activity or Val-boroPro inhibitor, and mediates CARD8 inflammasome activation. In response to pathogen-associated signals, the N-terminal part of CARD8 is degraded by the proteasome, releasing the cleaved C-terminal part of the protein (Caspase recruitment domain-containing protein 8, C-terminus), which polymerizes to initiate the formation of the inflammasome complex: the CARD8 inflammasome directly recruits pro-caspase-1 (proCASP1) independently of PYCARD/ASC and promotes caspase-1 (CASP1) activation, which subsequently cleaves and activates inflammatory cytokines IL1B and IL18 and gasdermin-D (GSDMD), leading to pyroptosis. Ability to sense HIV-1 protease activity leads to the clearance of latent HIV-1 in patient CD4(+) T-cells after viral reactivation; in contrast, HIV-1 can evade CARD8-sensing when its protease remains inactive in infected cells prior to viral budding. Also acts as a negative regulator of the NLRP3 inflammasome. May also act as an inhibitor of NF-kappa-B activation. [Caspase recruitment domain-containing protein 8]: Constitutes the precursor of the CARD8 inflammasome, which mediates autoproteolytic processing within the FIIND domain to generate the N-terminal and C-terminal parts, which are associated non-covalently in absence of pathogens and other damage-associated signals. [Caspase recruitment domain-containing protein 8, N-terminus]: Regulatory part that prevents formation of the CARD8 inflammasome: in absence of pathogens and other damage-associated signals, interacts with the C-terminal part of CARD8 (Caspase recruitment domain-containing protein 8, C-terminus), preventing activation of the CARD8 inflammasome. In response to pathogen-associated signals, this part is ubiquitinated by the N-end rule pathway and degraded by the proteasome, releasing the cleaved C-terminal part of the protein, which polymerizes and forms the CARD8 inflammasome (Probable). [Caspase recruitment domain-containing protein 8, C-terminus]: Constitutes the active part of the CARD8 inflammasome. In absence of pathogens and other damage-associated signals, interacts with the N-terminal part of CARD8 (Caspase recruitment domain-containing protein 8, N-terminus), preventing activation of the CARD8 inflammasome. In response to pathogen-associated signals, the N-terminal part of CARD8 is degraded by the proteasome, releasing this form, which polymerizes to form the CARD8 inflammasome complex: the CARD8 inflammasome complex then directly recruits pro-caspase-1 (proCASP1) and promotes caspase-1 (CASP1) activation, leading to gasdermin-D (GSDMD) cleavage and subsequent pyroptosis.
Synonyms: CARDINAL; TUCAN; DACAR; KIAA0955; NDPP1; NDPP; Dakar
Tractability: Small molecule: a structure with a bound ligand is known. PROTAC: UniProt records ubiquitination sites on it; ubiquitination databases record sites on it; its protein half-life has been measured.
Gene: Protein-coding gene on chromosome 19 (48,180,770 to 48,255,946, reverse strand). Ensembl gene ENSG00000105483.
Subcellular location: Cytoplasm; Nucleus; Inflammasome (Caspase recruitment domain-containing protein 8, C-terminus)
Subcellular location (Human Protein Atlas): Nucleoplasm
Pathways (Reactome):
Programmed Cell Death: Formation of apoptosome; Regulation of the apoptosome activity
Gene Ontology:
Molecular function: CARD domain binding; cysteine-type endopeptidase activator activity; molecular condensate scaffold activity; NACHT domain binding; pattern recognition receptor activity; protein binding; protein homodimerization activity
Biological process: antiviral innate immune response; CARD8 inflammasome complex assembly; defense response to virus; negative regulation of canonical NF-kappaB signal transduction; negative regulation of interleukin-1 beta production; negative regulation of lipopolysaccharide-mediated signaling pathway; negative regulation of NLRP3 inflammasome complex assembly; negative regulation of tumor necrosis factor-mediated signaling pathway; positive regulation of inflammatory response; positive regulation of interleukin-1 beta production; protein destabilization; self proteolysis; activation of innate immune response; inflammatory response; intrinsic apoptotic signaling pathway; regulation of apoptotic process
Cellular component: canonical inflammasome complex; CARD8 inflammasome complex; cytoplasm; NLRP3 inflammasome complex; nucleoplasm; nucleus; protein-containing complex; cytosol
Genetic constraint (gnomAD): Loss-of-function variants: 36 observed, 53.84 expected, observed/expected ratio (o/e) 0.67, 90% interval 0.51 to 0.88. The upper end of that interval is the gene's LOEUF score, 0.88, which puts it in group 3 of 6, group 1 being the genes least tolerant of losing a copy. Missense variants: 521 observed, 641.84 expected, observed/expected ratio (o/e) 0.81, 90% interval 0.75 to 0.87. Synonymous variants: 224 observed, 242.12 expected, observed/expected ratio (o/e) 0.93, 90% interval 0.83 to 1.03.
Homologues: Orthologues: chimpanzee CARD8 (92% identical), dog CARD8 (55% identical).
Diseases named in the same sentence as CARD8 in open-access papers:
CARD8 is named in the same sentence as 56 diseases in open-access papers, as found by Europe PMC text mining. Sharing a sentence is not in itself a finding about the gene and the disease. The quoted sentences say what the papers report.
acute myeloid leukemia (9 papers, 2018 to 2024). Acute myeloid leukemia (AML) is a group of neoplasms arising from precursor cells committed to the myeloid cell-line differentiation. "Val-boroPro triggers pyroptosis in primary acute myeloid leukemia (AML) cells by activating the inflammasome sensor protein CARD8 which then activates procaspase-1." (PMID 39620145, 2024). "Consistently, VBP and the more selective DPP8/DPP9 inhibitor 1G244 were shown to engage the inflammasome adaptor protein CARD8 to induce pyroptosis of a panel of acute myeloid leukemia (AML) cell lines and primary AML samples." (PMID 30718379, 2019). "As in acute myeloid leukemia (AML) cancer cell lines, we found that CARD8, and not NLRP1, mediates DPP8/9 inhibitor-induced pyroptosis in human T cells." (PMID 32796818, 2020). "Surprisingly, induction of pyroptosis in THP-1 cells and other AML (acute myeloid leukemia) cells by talabostat is mediated by CARD8 rather than by NLRP1, demonstrating that CARD8 is also able to form a type of inflammasome." (PMID 32640751, 2020).
viral infection (7 papers, 2022 to 2025). "In this study, we found that HIV-dependent CARD8 inflammasome activation during cell-free infection requires a cationic polymer like DEAE-dextran to facilitate efficient viral infection." (PMID 39229127, 2025). "Select genes that were highly expressed in COVID-19(+) TV specimens compared to COVID-19(+) PU and COVID-19(-) PU control groups play a central role in regulation of innate immune responses and defense to viral infection, including CARD8, IL1A, CD274, TRIM35, IRF7, and IFIH1." (PMID 37026002, 2023). "Our results also indicate that CARD8 evolution may dynamically reshape the repertoire of host-specific sensing of viral infection." (PMID 37289745, 2023). "Strikingly, we find that this same human SNP potentiates the ability of CARD8 to sense the 3C proteases (3Cpros) from a subset of human picornaviruses, suggestive of an evolutionary trade-off in CARD8 that may shape individual responses to viral infection." (PMID 37289745, 2023). "Our previous work investigating HIV-dependent CARD8 inflammasome activation used the cationic polymer DEAE-dextran, which is a common reagent used to enhance viral infection in cell culture." (PMID 39229127, 2025). "Importantly, the researchers also demonstrated that CARD8 knockout HAECs protected the underlying cardiomyocytes from CVB3 infection, indicating that the CARD8 inflammasome activity in CVB3-infected endothelial cells might increase the risk of viral infection in myocardium and even cause VMC." (PMID 37256114, 2023).
COVID-19 (6 papers, 2022 to 2024). A disease caused by infection with severe acute respiratory syndrome coronavirus 2. "Additionally, the distribution of the haplotypes of NLRP3, NLRC4, NLRP1, CARD8, CASP1, IL1B, and ATG16L1, with a frequency greater than 5% in HC, were similar between COVID-19 patients with mild, moderate, severe, and critical infection, and HC." (PMID 38612539, 2024). "Our data showing that SARS-CoV-2 infection activates the CARD8 inflammasome in THP-1 cells is consistent with findings that inflammasome activation contributes to severe COVID-19 and suggests that the CARD8 inflammasome in monocytes and macrophages contribute to inflammation in COVID-19 patients." (PMID 37289745, 2023). "In comparison to the COVID-19(-) PU controls, genes highly expressed in the TV group fell into categories that included neutrophil dysfunction (CD274, PADI2), inhibition of B and T cell responses (CD22, IRF4, ORAI1), and upregulation of pro-inflammatory response pathways (CARD8, MAPK7, IRF7, IFIH1)." (PMID 37026002, 2023).
atherosclerosis (5 papers, 2017 to 2026). A disease characterized by the build-up of fatty material and calcium deposition in the arterial wall resulting in partial or complete occlusion of the arterial lumen. "We also discuss the potential of targeting CARD8 as a therapeutic strategy for atherosclerosis, exploring the current preclinical and clinical evidence." (PMID 41659085, 2026). "The NOD-like Receptor Pyrin Domain-Containing 3 (NLRP3) inflammasome has emerged as a crucial mediator of inflammation in atherosclerosis, with caspase recruitment domain family member 8 (CARD8) acting as a key regulatory component." (PMID 41659085, 2026). "The Caspase activation and recruitment domain 8 (CARD8) protein is a component of innate immunity and overexpression of CARD8 mRNA was previously identified in atherosclerosis." (PMID 33154409, 2020). "Thus, this review summarizes the latest findings on the role of CARD8 in the pathogenesis of atherosclerosis, with a focus on the regulatory effects of this component on immune cells and inflammatory pathways." (PMID 41659085, 2026). "Due to the fact that CARD8 is overexpressed in plaque, we hypothesize that CARD8 is important for the immune modulation in atherosclerosis." (PMID 33154409, 2020). "LncRNA, ANRIL expression is associated with the chromosome 9p21 genotype and correlated with atherosclerosis severity and further ANRIL may also increase the risk of ischemic stroke through regulation of the CARD8 pathway." (PMID 28418905, 2017). "Therefore, elevated levels of CARD8 in atherosclerosis may therefore contribute to increased inflammation in the pathogenesis of atherosclerosis by upregulation of CXCL1, CXCL6, IL-6 and possibly also MCP-1, may aggravate atherosclerosis." (PMID 33154409, 2020). "In addition to Dpp4, there was an upregulation of a number of inflammation‐related genes including Card8, Card16, Gzma, Prf1, Il2rg, Il32, Cd52, and Ccl4 in CD4+ T cells isolated from patients with atherosclerosis." (PMID 36683148, 2023).
Crohn disease (4 papers, 2013 to 2022). A gastrointestinal disorder characterized by chronic inflammation involving all layers of the intestinal wall, noncaseating granulomas affecting the intestinal wall and regional lymph nodes, and transmural fibrosis. "Genetic variants in CARD8 gene have been reported to be associated with many infectious diseases such as inflammatory bowel disease, Crohn’s disease and tuberculosis." (PMID 32038701, 2019). "Patients with CARD8 mutations and excessive IL-1β production leading to Crohn's disease are in principle similar to patients with IL-10 abnormalities since in both cases increased NLRP3 inflammasome hyperactivity is due to lack of an inflammasome inhibitor." (PMID 30455704, 2018). "Of particular importance is the discovery that increased NLRP3 inflammasome activity occurring because of loss of CARD8 inhibition of the inflammasome can be a cause of Crohn's disease which responds only to treatment involving IL-1β inhibition." (PMID 30455704, 2018). "This discovery suggests the need for further studies to determine the frequency of excess IL-1β secretion in Crohn's disease patient populations due to CARD8 mutations or other abnormalities of the NLRP3 inflammasome." (PMID 30455704, 2018). "This study investigated the relationships between a mutation of the CARD8 gene encoding a component of inflammasome and antibody response in humans in the context of Crohn’s disease (CD) where anti-yeast glycan antibodies are well documented." (PMID 23506543, 2013). "Previous research has indicated that CARD8 is up-regulated in the mucosa of Crohn’s disease patients, which is consistent with our findings." (PMID 36685554, 2022). "Furthermore, our results mainly indicate that CARD8 might be involved in the regulation of the immune cell infiltration in Crohn’s disease, especially the CD56dim subset of natural killer cells." (PMID 36685554, 2022).
gout (4 papers, 2015 to 2021). A condition characterized by painful swelling of the joints, which is caused by deposition of urate crystals. "Functional variant rs2043211 in the gene encoding caspase recruitment domain-containing protein 8 (CARD8) demonstrated an association with gout in European and Chinese cohorts." (PMID 33926105, 2021). "Previous studies have identified polymorphisms in the NALP3 inflammasome, TLR-4, CARD8, IL-1β, IL-18, and CD14 genes to be associated with gout." (PMID 29023487, 2017).
HIV-1 infection (4 papers, 2023 to 2025). The type species of lentivirus and the etiologic agent of acquired immunodeficiency syndrome (AIDS). "Previous studies have also linked HIV-1-infection-induced inflammasome activation to CARD8 expression in macrophages and demonstrated that pyroptotic cell death and IL-1β secretion either required NNRTI-induced dimerization of Gag-Pol or Gag-Pol overexpresison and subsequent PR activation." (PMID 40920844, 2025). "Here, we investigated both host and viral determinants of CARD8 inflammasome activation upon HIV-1 infection." (PMID 39229127, 2025). "In this study and our prior work, we demonstrate that CARD8 is also the primary innate sensor during HIV-1 infection in myeloid cell types during cell-to-cell transmission." (PMID 39229127, 2025). "Nonetheless, these data, along with other recent work, strongly suggest that CARD8 is a major innate sensor of HIV-1 infection." (PMID 40522834, 2025). "Taken together, these data suggest that in the context of cell-to-cell transmission, CARD8 is likely the inflammasome-forming sensor that detects HIV-1 infection via incoming HIVPR activity in primary monocyte-derived macrophages." (PMID 39229127, 2025). "Similar to our observations with VbP, we found that IL-1β secretion, cell death, and CASP1 activation (as measured by FLICA assay) were significantly reduced in CARD8 KO versus WT THP-1 cells following HIV-1 infection." (PMID 37417868, 2023). "To test this hypothesis, we treated target cells with the HIVPR inhibitor LPV, which blocked CARD8 inflammasome activation by HIV-1 infection, reinforcing that CARD8 senses HIV-1PR activity." (PMID 37417868, 2023). "To further evaluate the role of the human-derived F59-F60 motif of CARD8 after HIV-1 infection, we used a doxycycline (dox)-inducible system to complement CARD8 KO THP-1 cells with either WT CARD8 or CARD8 cleavage mutants and probed for subsequent inflammasome activation." (PMID 37417868, 2023). "Our finding that HIV-1 infection is sufficient to induce inflammasome activation, along with the presence of CARD8 in relevant T cell populations, also suggests that CARD8 contributes to HIV pathogenesis." (PMID 37417868, 2023). "We found that inflammasome activation following cell-to-cell transmission of HIV-1 could be detected by 24 hours, which is delayed relative to our detection of CARD8 inflammasome activation 2 hours post cell-free HIV-1 infection in the presence of DEAE-dextran." (PMID 39229127, 2025). "Thus, human CARD8 detects the enzymatic activity of HIVPR by encoding a motif that functions as a HIVPR substrate, permitting a human-specific CARD8 inflammasome response to HIV-1 infection." (PMID 37417868, 2023). "It is also possible that IL-1β release after HIV-1-dependent CARD8 activation after HIV-1 infection could contribute to pathogenesis since IL-1β induces the differentiation of Th17 cells, a highly HIV-susceptible CD4+ T cell subtype, as well as the recruitment of other target immune cells." (PMID 37417868, 2023). "To gain additional insight into the nature of CARD8 inflammasome responses to HIV-1 infection, we performed a time-course following HIV-1 infection." (PMID 37417868, 2023). "To determine if inflammasome activation upon HIV-1 infection is dependent on CARD8, we generated clonal THP-1 CARD8 knockout (KO) cells via CRISPR/Cas9." (PMID 37417868, 2023). "We found that CARD8 KO THP-1 cells complemented with WT CARD8 underwent IL-1β secretion and cell death in response to both VbP and HIV-1 infection in a dox-dependent manner, confirming that HIV inflammasome activation is CARD8-dependent." (PMID 37417868, 2023). "To determine if CARD8 inflammasome activation can occur during HIV-1 infection in the absence of small molecule-induced HIV-1PR dimers, we infected the human leukemia monocytic cell line THP-1 at a multiplicity of infection (MOI) <1 and assayed for cell death (left) or IL-1β secretion (right)." (PMID 37417868, 2023).
HIV-1 infection (continued). "Because responses to HIV-1 infection were reduced to a similar level in both CARD8 KO cells and CASP1 KO cells, our findings suggest that the inflammasome response to HIV-1 infection in THP-1 cells is primarily dependent on CARD8, but independent of HIV-1 envelope." (PMID 37417868, 2023).
pneumococcal meningitis (3 papers, 2016 to 2023). An acute purulent infection of the meninges and subarachnoid space caused by Streptococcus pneumoniae, most prevalent in children and adults over the age of 60. "In a cohort of 435 pneumococcal meningitis patients and 416 controls we found that variation within CXCL1 and CARD8 were the strongest signals associated with pneumococcal meningitis susceptibility." (PMID 27432718, 2016).
psoriasis (3 papers, 2016 to 2020). An autoimmune condition characterized by red, well-delineated plaques with silvery scales that are usually on the extensor surfaces and scalp. "Single nucleotide polymorphisms (SNPs) in the NLRP3 gene, NLRP1, and caspase recruitment domain-containing protein 8 (CARD8) which is the negative regulator of caspase-1 activity, are also associated with susceptibility with psoriasis." (PMID 27941683, 2016). "NLRP3 rs10733113 and CARD8 rs2043211 were found to increase the risk of psoriasis in a Swedish population, supporting the hypothesis that inflammasome variation predisposes individuals to psoriasis." (PMID 32528469, 2020). "CARD8 represents a new signaling molecule involved in the regulation of caspase-1 and NF-κB activation, which play key roles in the development of psoriasis." (PMID 32104685, 2020). "Third, we only tested limited polymorphisms in the CARD8 gene, which may not be a critical locus for psoriasis but just near in LD to a causative locus." (PMID 32104685, 2020).